AR (androgen receptor)
Diseases named in the same sentence as AR in open-access papers (continued):
Sharing a sentence is not in itself a finding about the gene and the disease.
prostate carcinoma (continued). "Moreover, since AR and E2F1 share binding sites in prostate cancer cells and their co-occupancy is dependent on AR, a similar interaction between GR and E2F1 could occur in NEPC." (PMID 39027480, 2024). "Mechanistically, it is uncertain how menin promotes the growth of AR-negative prostate cancers." (PMID 39336822, 2024). "Moreover, while these forms of therapy are used for the treatment of metastatic castration-resistant prostate cancer (CRPC), none of these therapies specifically target prostate cancers that have androgen receptor-negative profiles." (PMID 38213538, 2023). "Proliferation assays were performed with VCaP and LNCaP cells (AR positive prostate cancer cell lines), DU145 cells (AR negative prostate cancer cell line) and HEK293 cells (immortalized embryonic kidney cells), while MDV3100 and vorinostat were used as the positive controls." (PMID 38004560, 2023). "Specifically, AR antagonists demonstrate contextual synthetic lethality with PARPi by modulating the expression of key HR proteins such as BRCA1/2 and RAD51, and potentially enhance the vulnerability of prostate cancer cells on alternative DNA repair mechanisms, such as PARP-mediated repair." (PMID 37812088, 2023). "Additionally, in androgen receptor (AR)-negative prostate cancer cells, the suppressive mechanisms are related to subtype d and e." (PMID 38173834, 2023). "Additionally, apalutamide, a second-generation androgen receptor antagonist, is used for the treatment of non-metastatic castration-resistant prostate cancer." (PMID 37679788, 2023). "AR promotes DNA damage repair in prostate cancer cells after radiation therapy and targeting AR pathway using AR signaling inhibitors (ASI) like Enzalutamide (Enz), Bicalutamide (Bic) are evolving as radiosensitization approaches in the management of prostate cancer." (PMID 36959798, 2023). "However, long-term anti-androgen receptor (AR) therapy was shown to alter the prostate cell lineage, leading to epithelial-mesenchymal transition (EMT), treatment resistance, and neuroendocrine (NE) differentiation (NED) of prostate cancer cells." (PMID 37142586, 2023). "Exploring the function of H3.3 in prostate cancer (PC), we found that knockout (KO) of H3.3 chaperone HIRA suppresses PC growth in vitro and in xenograft settings, deregulates androgen-induced gene expression and alters androgen receptor (AR) binding within enhancers of target genes." (PMID 37638746, 2023). "Functional studies using prostate cancer cell lines suggest that the expression of the Galectin-3 is not regulated by AR, but other hormones and their receptors, such as ER, could be involved in the regulation of the expression of the Galectin-3." (PMID 36936148, 2023). "Furthermore, KMT5A plays a role in the epithelial–mesenchymal transition (EMT) and enhances the invasiveness of prostate cancer cell line models, independent of the AR through its interplay with ZEB1." (PMID 37509260, 2023). "First, we still do not know whether AR is involved in the regulation of FEN1 phosphorylation or ubiquitin in prostate cancer." (PMID 37326412, 2023). "This form of prostate cancer often continues AR signaling that is not reliant on androgen ligands (i.e., androgen independent) by way of multiple mechanisms, including mutations in the receptor or copy-number variations, and is typically treated with androgen-receptor inhibitors (ARIs)." (PMID 37189720, 2023). "Studies on androgen synthesis inhibitors (e.g., abiraterone) and androgen receptor antagonists (e.g., enzalutamide) have found that these forms of hormone therapy are increasing the incidence of androgen receptor negative (ARneg), androgen-independent (AI) prostate cancers." (PMID 38213538, 2023). "We evaluated whether RBN2397 has potential utility in prostate cancer using biochemical approaches and cell growth assays in AR-positive (AR+) and AR-negative (AR−) prostate cancer lines." (PMID 37077937, 2023).
prostate carcinoma (continued). "IL-1β or TNFα inhibit the growth of androgen receptor (AR)+ LNCaP cells but not that of androgen-independent PC-3 human prostate cancer (PC) cell lines in co-cultivation with monolayers of human diploid fibroblast WI-38 cells derived from embryonic lung tissue." (PMID 37046676, 2023). "-AR-negative castration-resistant prostate cancer cell line (CRPC) as topoisomerase II catalytic inhibitor (88.9% growth inhibition at 20 μM) and by intercalating and binding to the DNA minor groove (IC50 = 0.13 ± 0.007 μM).-Sensitizes AR-positive CRPC cells to enzalutamide and taxanes." (PMID 37764304, 2023). "Hormone therapies like androgen receptor antagonists (e.g., enzalutamide) and androgen synthesis inhibitors (e.g., abiraterone) are increasing the occurrence of a subtype of prostate cancer that is negative for the androgen receptor and can progress via AI oncogenic signaling cascades." (PMID 38213538, 2023). "According to the literature, TFF3 acts as an oncogene because it regulates other genes (FOXA1, HER2, and AR) involved in EMT, thus promoting invasiveness, survival, and increased proliferation in multiple carcinomas such as gastric cancer, mammary carcinoma, and prostate cancer." (PMID 37900178, 2023). "Consequently, AR signaling has a suppressive role in the regulation of intracellular ROS in androgen-responsive prostate cancer cells but not in castration-resistant cells." (PMID 38155939, 2023). "Androgen-indifferent prostate cancer (AIPC) is a form of PCa with treatment-resistant phenotypes that do not rely on AR signaling and typically arise from mCRPC following treatment with ASIs, although they may arise de novo in treatment-naïve PCa." (PMID 37189720, 2023). "Similar to our findings, Tolmeijer and colleagues found a strong link between ctDNA at baseline and OS in a group of advanced castrate-resistant prostate cancer patients, but the changes from high to low ctDNA levels at 4 weeks of androgen receptor inhibition was not correlated with OS." (PMID 36813867, 2023). "Encouraged by the promising data, the present study aims to investigate the relationships between the core structure of 5,7,20-O-trimethylsilybin and their antiproliferative activities towards AR-positive (LNCaP) and AR-negative prostate cancer cell lines (PC-3 and DU145)." (PMID 37111288, 2023). "Progression of AR-dependent adenocarcinoma through lineage plasticity to AR-independent forms of prostate cancer, such as double-negative prostate cancer (DNPC) — lacking both AR expression and NEPC differentiation — or NEPC through lineage plasticity, is now increasingly recognized." (PMID 37440313, 2023). "18βGA repressed androgenic and survival responses in prostate cancer cells by inducing tumor-suppressive miR-488 and transcriptional downregulation of AR via modulating E2F transcription factor 3 (E2F3)α and serum response factor (SRF) activity on the androgen receptor promoter." (PMID 36903944, 2023). "Therefore, we speculate that the induction of PSMA that we observe in prostate cancer cells upon Duta treatment might be HOXB13 related and AR independent." (PMID 37569712, 2023). "It is important to identify anti-cancer compounds that can inhibit specific molecular targets to eradicate androgen-receptor negative (ARneg), androgen-independent (AI) prostate cancer, which is an aggressive form of prostate cancer with limited treatment options." (PMID 38213538, 2023). "Indeed, the PI3K pathway is directly responsible for AKT activation and provides an intrinsic bypass mechanism able to enhance both the survival and proliferation of prostate cancer cells lacking AR signaling, making these cells resistant to androgen therapy." (PMID 36835033, 2023).
prostate carcinoma (continued). "Androgen receptor signaling was reported to promote the PPP through mTOR-mediated upregulation of G6PD in human prostate cancer cell lines, and G6PD expression was closely correlated with prostate cancer progression using two animal models of Pten deletion/elevated mTOR pathway." (PMID 37802999, 2023). "In our previous study, we showed that vortioxetine did not directly promote the growth of either androgen-dependent or -independent prostate cancer cells in vitro, and did not interfere with the anti-proliferative activity of the androgen-receptor antagonist enzalutamide." (PMID 37788996, 2023). "JNJ-64619178 inhibits DNA damage repair in prostate cancer cells independent of their AR status." (PMID 36959798, 2023). "These analyses demonstrated that the RC43N and RC43T very significantly overlapped with AA nonmalignant prostate and prostate cancer AR cistromes, but not the EA prostate cancer AR cistrome, and LNCaP most significantly overlapped with the EA prostate cancer AR cistrome." (PMID 37082578, 2023). "On the other hand, PI3K or AKT inhibition might not be enough to significantly reduce tumor size in prostate cancer, and repression of the AR axis is also necessary for maximum effectiveness." (PMID 36835033, 2023). "The research also suggests that AR and ER transcriptionally upregulate the expression of MBOAT1 and MBOAT2, respectively, and inhibition of these receptors downregulates their transcriptional expression, sensitizing prostate cancer and breast cancer cells to ferroptosis." (PMID 37735316, 2023). "Androgen receptor (AR), MAPK, and WNT signaling cascades are among the major interplaying oncogenic signaling cascades that may activate the PI3K-AKT-mTOR pathway and thus promote prostate cancer growth and drug resistance." (PMID 36428613, 2022). "Moreover, recent evidence indicates that nuclear AR can be efficiently degraded by nuclear proteasomes in the absence of androgens in models of prostate cancer." (PMID 36277484, 2022). "As such, this suggests that the increase in cholesteryl esters may serve as an important source of cholesterol, via the actions of cholesteryl ester hydrolases, for de novo steroidogenesis and thereby influence AR-positive, androgen-independent (i.e., CRPC) prostate cancer cell growth." (PMID 35033184, 2022). "One pre-clinical research study observed that chronic AR activation, through testosterone-BSA exposure, enhanced paclitaxel microtubule disrupting dynamics, inhibited cell proliferation, and induced apoptosis in androgen sensitive and insensitive human prostate cancer cell lines." (PMID 35884386, 2022). "Interestingly, inhibition of the PI3K pathway in PTEN negative prostate cancers activates the AR pathway." (PMID 36551557, 2022). "In prostate cancer, it has been proposed that elevated E2F1 expression might contribute to the progression of hormone-independent PCa through its ability to repress the expression of the androgen receptor." (PMID 36230876, 2022). "AR itself is not included in this gene set, and the molecular mechanisms that initiate AR mRNA transcription remain a critical and unresolved issue and with possible important implications for the understanding of AR in prostate cancer and prostate CSCs." (PMID 35203681, 2022). "In order to address whether the effect of Gnmt deletion was based on prostate cancer cell-autonomous effects, we silenced GNMT in three independent PCa cell lines with differing AR status and GNMT levels (PC3, DU145, and LNCaP) using two different short hairpin RNAs." (PMID 35197445, 2022). "For example, nuclear translocation of epidermal growth factor receptor (EGFR) or androgen receptor (AR) associated with EVs released from prostate cancer cells and taken up by indolent receptor cells (i.e., cells without EGFR/AR) activated distinct signaling pathways in the latter." (PMID 36010551, 2022).
prostate carcinoma (continued). "In addition to prostate cancer, emerging data suggested that enzalutamide had an anticancer effect on TNBC, indicating that targeting AR might be a promising approach for TNBC." (PMID 36548336, 2022). "Our results indicated that ivermectin could block the R1881-induced AR activity in LNCaP and C4-2 cells without significantly reducing AR levels in various prostate cancer cell lines." (PMID 36050295, 2022). "Not surprisingly, most research on AR in prostate cancer has focused on its oncogenic functions." (PMID 36923279, 2022). "Therefore, further investigation of therapeutic strategies by co-targeting reciprocal interactions of AR and IGF1 pathways between epithelial tumor cells and surrounding tumor niches may improve clinical outcomes for advanced prostate cancer." (PMID 36323713, 2022). "In addition to DNA repair pathways, BRCA1/2 also could repress the progression of prostate cancer by inhibiting PI3K/AKT and MAP/ERK pathways, as well as MMP9 and AR signaling." (PMID 35734583, 2022). "Upon treatment with the dual PI3K/mTOR inhibitor DS-7423, PTEN wild-type prostate cancer CWR22/22RV1 cells upregulate expression of the proteins PSMA, mGluR1, and the tyrosine kinase receptor HER2, while PTEN-mutant LNCaP cells upregulate androgen receptor and HER3." (PMID 35086953, 2022). "Previous transcriptomic analysis of metastatic castration-resistant prostate cancer (mCRPC) has identified gene sets that can classify different subtypes of prostate cancer, including AR positive prostate cancer (ARPC), NEPC, and DNPC (negative for both AR and NE markers)." (PMID 36672609, 2022). "Darolutamide is a novel oral non-steroidal AR inhibitor with a unique chemical structure that binds to AR with high affinity and exhibits strong antagonistic activity, thereby inhibiting receptor function and the growth of prostate cancer cells." (PMID 36362304, 2022). "MYC is downstream of AR and promotes prostate cancer cell growth even in the absence of androgens." (PMID 35935969, 2022). "Notably, AR is the target of the drug Enzalutamide, which is indicated for men with an advanced stage of the disease, or that MYC is the target of BET bromodomain inhibitors and are generally effective in castration-resistant prostate cancer cases." (PMID 35164900, 2022). "Since the AR is activated by androgens, androgen deprivation therapy (ADT), which can be achieved either through surgical castration (orchiectomy) or chemical castration (using Gonadotropin-Releasing Hormone agonists or antagonists), is the mainstay treatment line for prostate cancer." (PMID 35740556, 2022). "Therefore, it appears that at least in some AR‐positive prostate cancer cells, AR is present in the nucleus even in the absence of androgen, and such androgen‐independent AR binds to the ZFHX3 promoter to repress its transcription." (PMID 34953044, 2022). "Androgen receptor plays a key role in prostate cancer that does not respond to castration therapy." (PMID 36012138, 2022). "In addition, we also evaluated the effect of ZIC5 on the metastasis in PC3 cells, an AR-negative PCa cell line that is widely used in prostate cancer research." (PMID 36127329, 2022). "In addition, the use of AR inhibitors is accompanied by an increase in the incidence rate of highly invasive AR negative prostate cancer." (PMID 36686485, 2022). "In addition to mediating downstream effector cascades that promote cancer growth and metastatic spread, the Wnt pathway has also been shown to cooperate with other cell signaling pathways to facilitate prostate cancer and CRPC transition, including the AR pathway." (PMID 35204808, 2022). "It is common for a NE prostate cancer phenotype to not express AR and PSA and common for amplification of the genes aurora kinase A (AURKA) and N-myc (MYCN, both of which were overexpressed in ACRJ-PC28 at RNA-seq level and MYC was detected at the protein level." (PMID 36643868, 2022).
prostate carcinoma (continued). "In this respect, selective AR modulators (SARM) are of interest because it is conceivable that some may possess the requisite androgenic anti-growth and immunomodulatory activities in prostate cancer cells and favorable anabolic properties in other tissues." (PMID 36923279, 2022). "At the same time, to explore the effects of castration on prostate cancer, VCaP cells were subjected to long-term treatment with enzalutamide at either low (2 μM) or high (20 μM) concentrations for at least four weeks, and the expression of NAT10, CDC6, and AR was measured." (PMID 35743017, 2022). "We note that we also found peptides from LBD1 and DNMT1, but further evaluation showed that these proteins did not exhibit as strong a difference in AR-expressing prostate cancer cells, and we therefore concentrated on NFIC and TBX3, which also interacted with FOXA1 in our other RIME experiments." (PMID 35550030, 2022). "This side effect of AR-targeting treatment may contribute in part to the limited improvements in overall survival observed in patients since 2012 despite the development and FDA approval of several new prostate cancer therapies." (PMID 35741020, 2022). "For example, Androgen Receptor (AR) targeting sgRNAs were significantly depleted in AR-dependent prostate cancer cell lines LNCaP and 22Rv1 while no change was observed in AR-negative cell line DU145 and TNBC cell lines suggesting that EPIKOL can distinguish tissue or cell line specific hits." (PMID 35973998, 2022). "Pioneered by the AR (Androgen receptor) degrader ARV-110 (NCT03888612) and ER (Estrogen receptor) degrader ARV-471 (NCT04072952), developed by Arvinas Inc. for the treatment of prostate cancer and breast cancer, respectively, the field has seen at least 15 degraders in a clinical trial." (PMID 35978859, 2022). "In addition to the involvement of the AR signaling events in tumorigenesis of GBM, the AR-signaling axis was also shown to participate in the oncogenesis of various types of cancers, especially prostate cancer." (PMID 36013056, 2022). "Besides, DU-145 is also AR-negative, and is often assayed in tandem with PC-3 to better assess the response of prostate cancer to chemotherapeutic agents." (PMID 36348374, 2022). "Moreover, in the LNCap prostate cancer cell line obtained through long-term incubation in an androgen-depleted environment, FGF5 protein levels are significantly increased, and the stimulation of AR reduces FGF5 levels in these cells." (PMID 36233155, 2022). "Nonetheless, it seems that while high AR activity is required for prostate cancer growth inhibition by BAT, it may not be sufficient, and future studies should assess additional factors that are required to confer sensitivity to BAT." (PMID 36194476, 2022). "Moreover, the castration resistant C4-2B cells and the AR-negative PC-3 cells represent the most characterized bone metastatic prostate cancer models." (PMID 36140255, 2022). "Furthermore, β-catenin is reported to directly bind the LBD of AR in a dihydrotestosterone (DHT)-dependent manner via its armadillo domain, resulting in increased AR-mediated transcriptional activity in AR-positive LNCaP prostate cancer cells." (PMID 35204808, 2022). "Notably, the PC-3 cell line is a prostate cancer cell that does not express the androgen receptor, and these findings suggest that Eeq does not exert its anti-prostate cancer effects through modulation of the androgen receptor signaling pathway." (PMID 36034825, 2022). "Accumulating evidence indicates that SENP1 is involved in the desumoylation of androgen receptor (AR), and that overexpression of SENP1 increases AR transcriptional activity, which has been found in >50% of high-grade precancerous prostate tissues, and in numerous prostate cancer cases." (PMID 35807394, 2022). "MeT strongly inhibited growth of prostate cancer cells expressing AR, but not AR-negative models." (PMID 36923279, 2022).